MFAP5 (microfibril associated protein 5)
Diseases named in the same sentence as MFAP5 in open-access papers (continued):
Sharing a sentence is not in itself a finding about the gene and the disease.
cancer (42 papers, 2015 to 2025). A tumor composed of atypical neoplastic, often pleomorphic cells that invade other tissues. "MFAP5 expression has also been reported in various fibroblast populations including cancer-associated fibroblasts." (PMID 40076432, 2025). "Two possible markers of cancer-associated fibroblasts (CAFs), MFAP5 and SVEP1, were upregulated in biopsies, and the expression of the last one was positively correlated with a longer OS." (PMID 39202425, 2024). "More recently, MFAP5 has been shown to be expressed at high levels in stromal fibroblasts of various human cancers, with higher expression linked to poorer outcomes." (PMID 37253753, 2023). "There has been recent interest in understanding the role of MFAP5 as it has been found to be highly expressed in stromal fibroblasts of various human cancers, with higher expression linked to enhanced cancer fibrosis, angiogenesis, and chemoresistance." (PMID 37253753, 2023). "Here, we find that prognostic microfibril associated protein 5 (MFAP5) is involved in activation of cancer-associated fibroblasts (CAFs)." (PMID 37156839, 2023). "CAF-secreted microfibrillar-associated protein 5 (MFAP5) promotes cancer cell EMT marker upregulation, migration, and invasion via the Notch1 pathway." (PMID 34337083, 2021). "Most previous studies claimed that MFAP5 is majorly secreted by stroma cells like cancer-associated fibroblasts (CAFs)." (PMID 32047565, 2020). "In murine models of ovarian and PDAC cancers, inhibition of MFAP5 with monoclonal antibodies is associated with a decrease in the number of CAFs and microvessels, but also with increased sensitivity to paclitaxel." (PMID 33114328, 2020). "Thus, changes in the expression of many of our proposed markers (including COL6A3, MFAP2 and MFAP5) can indicate the transition of normal fibroblasts to a cancer-associated state (e.g., in in vitro experiments)." (PMID 36263012, 2022). "The MFAP5 protein influences properties of the extracellular matrix in cancer, including collagen deposition, and its targeting should be suitable for adjuvant cancer therapy." (PMID 40971055, 2025). "Activation of gene MFAP5 across all CAFs (except oMELF) is typical of fibroblasts present in malignant tumours, where these cells promote malignant cells to form metastases." (PMID 40971055, 2025). "In recent years, many studies have shown that CAF‐derived MFAP5 plays a paracrine role in the progression of various cancers." (PMID 36855786, 2023). "Reciprocally, activated myeloid cells regulate the activation of MFAP5 + fibroblasts in a positive feedback mode by secreting cancer-promoting ligands that contain EGF superfamily proteins and NAMPT." (PMID 37344903, 2023). "MFAP5’s role in cancer is poorly characterized, although there are some preliminary data concerning its possible role in OC." (PMID 36555638, 2022). "When MFAP5 was assessed in cancer cells, eight samples (7.41%) showed strong expression (score 3), 33 samples (30.55%)—moderate expression (score 2), and 67 samples (62.04%)—weak expression (score 1)." (PMID 36555638, 2022). "Similar to the function of Mfap5, loss of PEDF in cancer cells is associated with poor prognosis and metastasis." (PMID 33828460, 2021). "MFAP5 secreted by CAFs activates FAK/cAMP response element-binding protein (CREB)/troponin C type 1 (TNNC1) via SOCE to enhance cancer metastasis." (PMID 36046433, 2021). "MFAP5 was strongly expressed in fibroblastic cancers such as breast, ovarian, sarcoma, pancreatic and lung cancers." (PMID 33114328, 2020). "Similar results were found in all samples, and the relative expression patterns via pan-cancer analysis showed that MFAP5 was an important gene in tumorigenesis." (PMID 32457800, 2020). "Second, after the stimulation of hypoxia and overexpression of MFAP5 in the first place, what is the feedback mechanism of cancer cell?" (PMID 32047565, 2020).
cancer (continued). "As a potentially crucial miRNA that interacted with MFAP5, miR-200b-3p also showed relatively consistent expression across diverse cancer types." (PMID 32457800, 2020). "The relationship between MFAP5 and poor prognosis has been proven in many cancers as well as HNSCC 27-29." (PMID 32047565, 2020). "In contrast to MFAP2, the expression of MFAP4 and MFAP5 was downregulated in cancer tissues." (PMID 40657371, 2025). "Microfibril-Associated Glycoprotein 5 (MFAP5) has not been described in testis cells but has been identified in cancer associated fibroblasts where it is associated with extracellular matrix remodeling." (PMID 40569389, 2025). "MFAP1, MFAP2 and MFAP3 were up-regulated in both EAC and ESCC, while MFAP4 and MFAP5 were down-regulated in cancer tissues, indicating that MFAP2 might play crucial role in ESCC." (PMID 40657371, 2025). "MFAP5 has been shown to play a role in EMT process in cancer progression." (PMID 39759103, 2024). "Hence, further studies are required to elucidate the conserved features of MFAP5 + fibroblasts in various cancers." (PMID 37344903, 2023). "Furthermore, myeloid cells can transmit cancer-promoting signals to MFAP5 + fibroblasts via the NAMPT-ITGA5/ITGB1 pair (VISFATIN signaling pathway)." (PMID 37344903, 2023). "The alteration of MFAP5 protein and THBS4 protein from fibroblast might be associated with the migration of ENCC—similar to the cancer cells." (PMID 36738110, 2023). "SERPINE2 and MFAP5 have both been reported to promote the EMT process in cancer." (PMID 37283740, 2023). "In this study, we investigated the biological properties of MFAP5 + fibroblasts in cancer tissues." (PMID 37344903, 2023). "In fact, many target genes of YAP have been proved to participate in cancer-associated angiogenesis through activation of ECs, especially the cytokines such as CTGF, cyr61, MFAP5, and angiopoietin-2, which could secreted by cancer cells." (PMID 36226237, 2022). "MFAP5-positive cancer-associated fibroblasts (CAFs) promote the invasiveness and metastatic potential of GC cells by facilitating epithelial-mesenchymal transition (EMT), with elevated MFAP5 expression potentially serving as an important marker for GC staging and diagnosis." (PMID 41458606, 2025). "However, when analyzing MFAP5 expression on ovarian tissue arrays (US Biomax, Inc., Derwood, MD, USA), we observed elevated levels of MFAP5 in some proportion of tissues of every type (normal, benign, and cancer), both in the stromal and epithelial compartment." (PMID 36555638, 2022). "Thus, we also analyzed MFAP5 expression in the tissue array with different stages of fallopian tube neoplasia, from normal and inflamed epithelium, through benign hyperplasia, to cancer." (PMID 36555638, 2022). "However, the role of MFAP5 in these cancers remains to be elucidated." (PMID 27713166, 2017). "In bladder cancer and oral squamous cell carcinoma, MFAP5 secreted by CAFs activates NOTCH2/HEY1, ERK and PI3K signaling pathways directly, promoting the proliferation, migration and invasion of cancer cells." (PMID 33114328, 2020). "As for the circ_0012586/miR-200b-5p/MFAP5 pathway, there was still no report about circ_0012586 and cancer." (PMID 40959103, 2025). "To delve deeper into the MFAP5-regulated signaling pathway, we conducted a literature review and found that MFAP5 might activate the Notch2 and or HEY1 in other cancer type and Notch2 has been recognized as an oncogene that enhances invasion in GC." (PMID 39524442, 2024). "Surprisingly, strong stromal MFAP5 expression was prevalent in non-cancerous fallopian tube samples, while not in cancer samples." (PMID 36555638, 2022). "Although the function of MFAP5 has not been well established in both CAFs and GC, its oncogenic role and negative impact on patients’ clinical outcomes have been widely supported in other types of cancer." (PMID 39524442, 2024).
cancer (continued). "In addition, it is still not known whether MFAP5 + fibroblasts are conserved subclusters residing in distinct cancer types." (PMID 37344903, 2023).
metabolic disorders (1 paper, 2024). "Further research is warranted to elucidate the mechanisms underlying MFAP5’s involvement in both CAVD and metabolic disorders." (PMID 39749331, 2024).
MFAP5 also shares sentences with these, for which no sentence is quoted: lipoma (3 papers); cardiovascular disease (2); leiomyosarcoma (2); prostate carcinoma (2); benign ovarian tumor (1); benign tumors (1); cardiac hypertrophy (1); dilated cardiomyopathy (1); endometrial cancer (1); gynecological diseases (1); idiopathic pulmonary fibrosis (1); infection (1); Intellectual disability (1); lung disease (1); lung fibrosis (1); meningioma (1); metastatic tumors (1); muscular disorders (1); neurodegenerative disease (1); neutropenia (1); prostate tumors (1); psoriasis (1); Thoracic Aortic aneurysm and dissection (1); uterine tumors (1).